AATF (apoptosis antagonizing transcription factor)
Description:
Part of the small subunit (SSU) processome, first precursor of the small eukaryotic ribosomal subunit. During the assembly of the SSU processome in the nucleolus, many ribosome biogenesis factors, an RNA chaperone and ribosomal proteins associate with the nascent pre-rRNA and work in concert to generate RNA folding, modifications, rearrangements and cleavage as well as targeted degradation of pre-ribosomal RNA by the RNA exosome. May function as a general inhibitor of the histone deacetylase HDAC1. Binding to the pocket region of RB1 may displace HDAC1 from RB1/E2F complexes, leading to activation of E2F target genes and cell cycle progression. Conversely, displacement of HDAC1 from SP1 bound to the CDKN1A promoter leads to increased expression of this CDK inhibitor and blocks cell cycle progression. Also antagonizes PAWR mediated induction of aberrant amyloid peptide production in Alzheimer disease (presenile and senile dementia), although the molecular basis for this phenomenon has not been described to date.
Synonyms: CHE1; DED; CHE-1; BFR2
Tractability: Small molecule: a structure with a bound ligand is known. PROTAC: ubiquitination databases record sites on it; its protein half-life has been measured.
Gene: Protein-coding gene on chromosome 17 (36,948,925 to 37,056,874, forward strand). Ensembl gene ENSG00000275700.
Subcellular location: Nucleus, nucleolus
Subcellular location (Human Protein Atlas): Nucleoli; Nucleoplasm
Pathways (Reactome):
Signal Transduction: NRAGE signals death through JNK
Gene Ontology:
Molecular function: leucine zipper domain binding; protein binding; RNA binding; transcription coactivator activity
Biological process: ribosomal small subunit biogenesis; maturation of SSU-rRNA; endoplasmic reticulum unfolded protein response; positive regulation of DNA-templated transcription
Cellular component: cytoplasm; nucleolus; nucleus; small-subunit processome; transcription regulator complex
Genetic constraint (gnomAD): Loss-of-function variants: 46 observed, 56.92 expected, observed/expected ratio (o/e) 0.81, 90% interval 0.64 to 1.03. The upper end of that interval is the gene's LOEUF score, 1.03, which puts it in group 4 of 6, group 1 being the genes least tolerant of losing a copy. Missense variants: 604 observed, 666.48 expected, observed/expected ratio (o/e) 0.91, 90% interval 0.85 to 0.97. Synonymous variants: 246 observed, 239.76 expected, observed/expected ratio (o/e) 1.03, 90% interval 0.92 to 1.14.
Homologues: Orthologues: chimpanzee AATF (99% identical), macaque AATF (97% identical), dog AATF (89% identical), rabbit AATF (88% identical), pig AATF (88% identical), guinea pig AATF (86% identical), mouse Aatf (78% identical), rat Aatf (77% identical), tropical clawed frog aatf (55% identical), zebrafish aatf (53% identical).
Diseases named in the same sentence as AATF in open-access papers:
AATF is named in the same sentence as 53 diseases in open-access papers, as found by Europe PMC text mining. Sharing a sentence is not in itself a finding about the gene and the disease. The quoted sentences say what the papers report.
hepatocellular carcinoma (5 papers, 2022 to 2025). A malignant tumor that arises from hepatocytes. "Altered AATF expression has been observed in various cancers, including tumors, colorectal cancer (CRC), lung cancer (LC), and hepatocellular carcinoma (HCC), where its overexpression is associated with poor prognosis." (PMID 39911629, 2025). "Divya P. Kumar (JSS Medical College, Mysuru) presented work on elucidating the molecular pathway involving AATF and evaluated AATF as a potential therapeutic target in steatohepatitis and hepatocellular carcinoma." (PMID 39140283, 2024). "AATF has been shown to be overexpressed in a variety of cancer tissues, such as breast cancer, multiple myeloma, leukemia, lung cancer, hepatocellular carcinoma, and head and neck squamous cell carcinoma, and its level increases during disease progression." (PMID 36275893, 2022). "Additionally, reducing AATF levels significantly reduced hepatocellular carcinoma cell oncogenic properties, such as proliferation, migration, and angiogenesis, and reduced cell death." (PMID 36275893, 2022).
neuroblastoma (4 papers, 2016 to 2022). Neuroblastoma (NB) is the most common solid, extracranial childhood tumor. "Most neuroblastoma patients express AATF gene amplification, and a high level of AATF is linked to a poor prognosis and reduced survival." (PMID 36275893, 2022). "Evidence has indicated that increased expression levels of AATF were found in various cancerous tissues and are negatively correlated with patient survival in neuroblastomas." (PMID 31152681, 2019). "More recently, cell lines derived from neuroblastoma patients were shown to overexpress AATF." (PMID 32587828, 2020).
breast carcinoma (3 papers, 2009 to 2025). "Based on its biological function, and direct interaction with several known breast cancer risk factors, AATF is a good candidate gene for being involved in heritable cancer susceptibility." (PMID 20025740, 2009). "In the current study, the whole coding region of the AATF gene was systematically screened for mutations in 121 breast cancer families." (PMID 20025740, 2009). "The aim of our study was to determine the relationship between breast cancer susceptibility and potential alterations in the AATF candidate gene, which plays an important role in the maintenance of genomic integrity and cell-cycle checkpoint control." (PMID 20025740, 2009). "Because of its influence on vital cellular functions it was considered possible that mutations in the AATF gene might contribute to hereditary disposition to breast cancer." (PMID 20025740, 2009). "Based on its biological function, we wanted to determine whether AATF germline mutations are involved in hereditary susceptibility to breast cancer." (PMID 20025740, 2009). "However, a small study like this cannot exclude the possibility of rare mutations in AATF that might predispose to breast cancer, but based on our findings, they unlikely make any sizeable contribution to cancer predisposition." (PMID 20025740, 2009). "For instance, ETV1 is associated with prostate cancer; RFX3-AS1, MRPS30, MRPS30-DT, and MIR3201 are associated with breast cancer; MIR548H4, AATF, and APCDD1L-DT are associated with lung cancer." (PMID 40440618, 2025). "AATF is also a regulator of tumor cell survival and tumor progression, and studies have found that silencing AATF promotes apoptosis in breast cancer cells." (PMID 36275893, 2022). "The observed AATF gene alterations lacked association with breast cancer risk and therefore mutations in this gene are likely not to play a significant role in hereditary predisposition to this malignancy." (PMID 20025740, 2009). "AATF sequence alterations have not previously been studied in relation to breast cancer predisposition." (PMID 20025740, 2009).
lung carcinoma (3 papers, 2022 to 2025). "Prior research has demonstrated that high AATF expression can lead to the generation of reactive oxygen species (ROS), which amplify YY-1/EGFR/MnSOD signaling and enhance cancer cell invasion in lung cancer." (PMID 39911629, 2025).
dyslipidemia (2 papers, 2024 to 2026). "This study shows that inhibition of TNF‐α converting enzyme (TACE) by Marimastat reduces liver injury, dyslipidemia, AATF expression, and oncogenic signaling, effectively preventing hepatocarcinogenesis." (PMID 38558505, 2024). "Interestingly, TACE inhibition by Marimastat reduced liver injury, dyslipidemia, AATF expression, and oncogenic signaling, effectively preventing hepatocarcinogenesis." (PMID 38558505, 2024).
head and neck squamous cell carcinoma (2 papers, 2019 to 2022). A squamous cell carcinoma that arises from any of the following anatomic sites: lip and oral cavity, nasal cavity, paranasal sinuses, pharynx, larynx, and salivary glands. "For example, a 7-mRNA signature (AATF, APP, GNPDA1, HPRT1, LASP1, P4HA1 and ILF3) of head and neck squamous cell carcinoma (HNSCC) shows a moderate predictive ability for 5-year OS (AUC for training set, 0.75; testing set, 0.66)." (PMID 31396442, 2019).
leukemia (2 papers, 2020 to 2022). A malignant (clonal) hematologic disorder, involving hematopoietic stem cells and characterized by the presence of primitive or atypical myeloid or lymphoid cells in the bone marrow and the blood. "AATF (also known as CHE1) participates in several cellular pathways, such as 40S ribosomal subunit synthesis in complex with NGDN (p = 0.0014, FC 0.95) and NOL10 (p = 0.0007, FC 0.85), and high AATF expression has been linked to variants of leukemia." (PMID 32192169, 2020).
lung adenocarcinoma (2 papers, 2020 to 2022). A carcinoma that arises from the lung and is characterized by the presence of malignant glandular epithelial cells. "Interestingly, the inducible knockout of AATF in existing carcinomas halted tumor growth in vivo and significantly increased the overall survival rate in a mouse model of adenovirus-induced lung adenocarcinoma." (PMID 32587828, 2020).
nephronophthisis (2 papers, 2020). Progressive tubulointerstitial injury, inherited in an autosomal recessive pattern, caused by mutations in genes involved in ciliary function, which may result in an end stage renal failure. "Interestingly, loss of AATF in the distal nephron resembled a clinical and histopathological phenotype of nephronophthisis (NPH) in our mouse model." (PMID 32587828, 2020). "Largely identified in nephronophthisis, mutations within DDR genes such as ZNF423, CEP164, NME3, and AATF are sufficient to cause disease via ciliary dysfunction." (PMID 32351541, 2020). "In addition, the close resemblance of the proximal tubule AATF knockout with human nephronophthisis suggests the DDR as a potential therapeutic target in order to extend the currently limited therapeutic options for NPH patients and halt the progression to chronic kidney disease." (PMID 32587828, 2020).
bladder urothelial carcinoma (1 paper, 2022). "The immune checkpoints PD-1, PD-L1, and CTLA4 were positively correlated with AATF expression in bladder urothelial carcinoma (BLCA), kidney chromophobe (KICH), and prostate adenocarcinoma (PRAD)." (PMID 36275893, 2022).
breast-ovarian cancer (1 paper, 2009). "The study of 121 breast or breast-ovarian cancer families revealed altogether seven different germline changes in the AATF gene." (PMID 20025740, 2009).
cervical cancer (1 paper, 2024). A primary or metastatic malignant neoplasm involving the cervix. "In conclusion, while further studies are needed to define the mechanisms underlying AATF action, our results provide novel evidence of the effect of AATF on ciliogenesis and VBL resistance through the regulation of NPHP3 and IFT88 expression in HeLa cervical cancer cells." (PMID 39408701, 2024).
colorectal cancer (1 paper, 2022). A primary or metastatic malignant neoplasm that affects the colon or rectum. "AATF has also been reported overexpressed in various cancerous tissues, including lung and colorectal cancer, as well as lymphomas." (PMID 36291689, 2022).
DNA repair disorders (1 paper, 2025). "Enrichment in DNA repair disorders emphasized AATF’s potential role in maintaining genomic stability." (PMID 39911629, 2025).
endometrial carcinoma (1 paper, 2020). A malignant tumor arising from the epithelium that lines the cavity of the uterine body. "In addition, endometrial carcinoma samples exhibited a nuclear accumulation of AATF, suggesting activation of the AATF-mediated transcriptional program." (PMID 32587828, 2020).
gallbladder cancer (1 paper, 2024). "While TGF‐β signalling has been extensively studied in various tumour contexts, research on AATF, particularly in the context of gallbladder cancer, remains limited." (PMID 39428382, 2024).
glioblastoma multiforme (1 paper, 2022). "The protein phosphorylation level of AATF at 4 sites, including S203, S316, S320, and S321, was changed in six tumors (BRCA, glioblastoma multiforme (GBM), LIHC, HNSC, KIRC, and LUAD) with data in the CPTAC database on the UALCAN website." (PMID 36275893, 2022).
jaw cysts (1 paper, 2026). "The identified 6 proteins, namely CD79A, CD5, KRR1, UTP20, AATF, and WDR43 - may be closely associated with the pathogenesis of jaw cysts." (PMID 42175431, 2026). "UTP20, AATF, and CD5 may represent potential candidate biomarkers associated with jaw cysts." (PMID 42175431, 2026).
lymph node metastasis (1 paper, 2025). "AATF was significantly overexpressed in OSCC, and high AATF expression correlated with adverse clinicopathological features, including histologic grade and lymph node metastasis." (PMID 39911629, 2025).
non‐alcoholic fatty liver disease (1 paper, 2024). "Keeping that objective insight, we had previously investigated the regulatory role of AATF in MASH‐HCC and found that hepatic AATF was upregulated in the diet‐induced animal model of non‐alcoholic fatty liver disease (DIAMOND)." (PMID 38558505, 2024).
Obesity (1 paper, 2024). Accumulation of substantial excess body fat. "Previously, we demonstrated that obesity‐induced proinflammatory cytokine (TNF‐α) upregulates AATF expression via SREBP1." (PMID 38558505, 2024).
ovarian carcinoma (1 paper, 2008). A malignant neoplasm originating from the surface ovarian epithelium. "In both subtypes of the ovarian carcinoma patients, three additional clusters of proteins including CLU, cleaved β chains of HAP (HAPc) and a different cluster of AATf spots were detected." (PMID 18637207, 2008).
prostate adenocarcinoma (1 paper, 2022). "Elevated AATF expression was also a risk factor for DFS in 4 tumors, including ACC, KIRP, LIHC, and prostate adenocarcinoma (PRAD) (ACC (HR = 3.1, P = 0.0023), KIRP (HR = 2, P = 0.021), LIHC (HR = 1.6, P = 0.0016), and PRAD (HR = 1.6, P = 0.032))." (PMID 36275893, 2022).
sarcoma (1 paper, 2022). A usually aggressive malignant neoplasm of the soft tissue or bone. "We found that the expression of AATF was negatively correlated with the infiltration of cancer-associated fibroblasts in sarcoma (SARC), testicular germ cell tumors (TCGT), and thymoma (THYM)." (PMID 36275893, 2022).
Wolfram syndrome 1 (1 paper, 2010). "These include the following antiapoptotic genes: AATF (antiapoptosis-inducing transcription factor) and WFS1 (Wolfram syndrome 1)." (PMID 20585452, 2010).
cancer (15 papers, 2008 to 2025). A tumor composed of atypical neoplastic, often pleomorphic cells that invade other tissues. "We also observed significant associations with retinoblastoma (RB) genes in cancer, implicating AATF in the regulation of cell cycle checkpoints." (PMID 39911629, 2025). "Prior studies have established an association between AATF expression and decreased survival rates across various cancers." (PMID 39911629, 2025). "We investigated the regulatory role of AATF on angiogenesis, a major hallmark of cancer, which is responsible for the rapid recurrence and poor survival rate in HCC patients." (PMID 37361585, 2023). "We found that the expression of AATF was higher in cancer than in normal tissues, and it was also associated with genes related to immune regulation." (PMID 36275893, 2022). "AATF expression levels in various cancer types were significantly correlated with the infiltration levels of cancer-associated fibroblasts, endothelial cells, CD4+ T cells, B cells, myeloid dendritic cells, eosinophils, and macrophages." (PMID 36275893, 2022). "Both copy number gains and high expression levels of AATF were associated with worse prognosis or relapse of malignant tumors." (PMID 32587828, 2020). "To closely estimate the association between AATF expression and the tumor microenvironment in the pan-cancer dataset, we further investigated the relationship between AATF expression and immunomodulation-related genes, including immune checkpoint, immunostimulatory, and immunosuppressive genes." (PMID 36275893, 2022). "Therefore, we explored the correlation of AATF expression levels with immune infiltration of cancer-associated fibroblasts, endothelial cells, CD4+ T cells, B cells, myeloid dendritic cells, eosinophils, and macrophages." (PMID 36275893, 2022). "Two of these three other proteins are linked to AATF within this network, the AATF protein being involved in ribosome biogenesis, checkpoint control/DNA repair, and regulation of apoptosis, and even being regarded as a possible therapeutic target in cancer treatment." (PMID 38791118, 2024). "AATF may be a risk factor for poor prognosis across cancers." (PMID 36275893, 2022). "Collectively, cancer cell survival following VBL treatment is regulated by PC formation via AATF-mediated expression of IFT88 and NPHP3." (PMID 39408701, 2024). "The ability of Marimastat to suppress the transition of inflammation to cancer in WD/CCl4 mice prompted us to examine the effect of Marimastat on the AATF‐mediated progression of MASH to HCC." (PMID 38558505, 2024). "AATF levels were found to be elevated in various cancers such as breast cancer, leukemia, lung cancer, Wilm’s tumor, osteosarcoma, and neuroblastoma, and their level increased during disease progression." (PMID 37361585, 2023). "In cancer, AATF expression is generally higher than that in normal tissue, and it is also associated with immunomodulation-related genes." (PMID 36275893, 2022). "This study revealed the relationship between AATF and tumor-infiltrating immune cells and investigated the immune status of cancer patients by detecting the expression of AATF." (PMID 36275893, 2022). "Comparing the protein expression of AATF between cancer and normal tissues, AATF was elevated in 8 of the 10 tumors (P < 0.05)." (PMID 36275893, 2022). "Next, TCGA and GTEx data were combined to compare the expression of AATF in pan-cancer and normal tissues." (PMID 36275893, 2022). "Apoptosis-antagonizing transcription factor (AATF) participates in tumor progression in multiple cancer types." (PMID 36275893, 2022). "In this study, we used multiple TCGA-based tools to comprehensively analyze the expression signature of AATF in different types of cancer for the first time." (PMID 36275893, 2022). "Clearly, AATF plays a critical role in the progression of cancer, possibly by preventing apoptosis induction and promoting cell survival." (PMID 36275893, 2022).